GFAP (glial fibrillary acidic protein)
Diseases named in the same sentence as GFAP in open-access papers (continued):
Sharing a sentence is not in itself a finding about the gene and the disease.
hemorrhagic stroke (continued). "Although astrocytes have differential roles in the recovery patterns of ischemic and hemorrhagic stroke, the long-term GFAP-positive astrocytic plasticity could be similar after both ischemic and hemorrhagic stroke." (PMID 33069238, 2020). "However, during the first 2 h, GFAP sensitivity for detecting hemorrhagic stroke is low, which makes this marker useless in diagnosis of the earliest phase of this pathology." (PMID 31701356, 2020). "In addition to being useful in diagnosing hemorrhagic stroke, GFAP could have some value in diagnosing early phase of traumatic brain injury." (PMID 31701356, 2020). "Glial fibrillary acidic protein (GFAP), an astrocytic structural protein, is established in hemorrhagic stroke and traumatic brain injury, but its role in AIS remains incompletely defined." (PMID 41827388, 2026). "In hemorrhagic stroke (HS), the disruption of the BBB leads to astrocyte damage and the subsequent release of GFAP into the bloodstream." (PMID 40136933, 2025). "Brain-specific proteins, such as glial fibrillary acidic protein (GFAP) and S100β, have shown promise in differentiating between ischemic and hemorrhagic stroke." (PMID 39493062, 2024). "The ability of GFAP to differentiate between AIS and hemorrhagic stroke (ICH and SAH) is well established in selected cohorts consisting only of the two pathologies in question with or without healthy controls." (PMID 36604741, 2023). "In another study, a combination of absolute GFAP levels and rate of change ruled out hemorrhagic stroke with a negative predictive value of 98.4%." (PMID 40900222, 2025). "While not directly studied in our reviewed papers, GFAP has shown promise in differentiating between ischemic and hemorrhagic stroke." (PMID 39493062, 2024). "In our study, we were unable to reproduce findings showing that GFAP was able to rule out hemorrhagic strokes in our patient cohort with all NIHSS scores included." (PMID 36604741, 2023). "Meanwhile, the results of the quantitative analysis of immunostaining showed that compared with the sham group, the mean fluorescent intensity and positive cell numbers of GFAP and IBA1 in the perilesion site were markedly elevated at 7, 14, 21, and 28 days after hemorrhagic stroke." (PMID 34530836, 2021).
Hydrocephalus (40 papers, 2007 to 2025). Hydrocephalus is an active distension of the ventricular system of the brain resulting from inadequate passage of CSF from its point of production within the cerebral ventricles to its point of absorption into the systemic circulation. "Elevated GFAP levels associated with hydrocephalus indicate reactive astrogliosis, which occurs in reaction to mechanical stress and damage produced by ventricular enlargement and abnormal CSF dynamics." (PMID 40722587, 2025). "At the same time, the possibility of using GFAP protein levels as a diagnostic tool for hydrocephalus is currently being explored." (PMID 23217034, 2012). "Inversely, gene knockdown of Ecrg4 in developing zebrafish embryos caused increased proliferation of GFAP-positive cells and induced a dose-dependent hydrocephalus-like phenotype that could be rescued by co-injection of antisense morpholinos with Ecrg4 mRNA." (PMID 21349154, 2011). "The association between severity of hydrocephalus and high GFAP and S100B concentrations suggests that these markers may be sensitive to transient injury due to the mechanical effect of dilating ventricles on the parenchyma, often accompanied by the opposing pressure from brain edema." (PMID 28605426, 2017). "Immunofluorescence staining results demonstrated that GFAP‐positive astrocytes were activated in both the corpus callosum and the periventricular area after hydrocephalus induction." (PMID 41236114, 2025). "Due to the relevance of the astrocytic reaction in hydrocephalus, the quantification of astrocytes (GFAP-positive cells) was carried out in brain sections 4 and 14 days after the treatment." (PMID 36982724, 2023). "Heterozygous Foxj1 mutant mice with hydrocephalus showed increased numbers of GFAP+ cells in the ependymal layer of the lateral ventricles." (PMID 37620636, 2023). "Astrocytic activation (GFAP stain) in the untreated hydrocephalus group were attenuated in the vanadium-treated groups under the GFAP stain." (PMID 36846142, 2023). "TSK dysfunction can result in hydrocephalus in both mice and humans, and our research suggested that aberrant splicing in LV GFAP+ stem/progenitor cells contributed to disease progression." (PMID 36478736, 2022). "The role of TSK, in modulating splicing and developmental signaling mediators in GFAP+ stem/progenitor cells, offers crucial understanding into aberrant LV development during hydrocephalus." (PMID 36478736, 2022). "On day 28 after kaolin injection, the numbers of GFAP‐positive cells and Iba‐1‐positive cells were increased in both cortex and hippocampus in the hydrocephalus group compared with the sham group." (PMID 34374150, 2021). "This trend contrasted with the overexpression of proteins implicated in metabolism and in the astrocyte reaction, as expected for hydrocephalus according to the literature, such as GFAP and vimentin and the NG2 antigen, the latter present in OPCs." (PMID 34215285, 2021). "In the hydrocephalus group, GFAP expressions increased from day 7 (7.47 ± 0.77) to day 21 (10.21 ± 0.10)." (PMID 32684804, 2020). "The hydrocephalus group showed a significantly higher GFAP expression (P < 0.001) than in the normal group (2.96 ± 0.28)." (PMID 32684804, 2020). "Further studies of these mice confirmed that GFAP Cre Rfx4flox/+ mice exhibited hydrocephalus with SCO dysplasia." (PMID 29298325, 2018). "The highest lumbar GFAP and S100B concentrations were greater in moderate-to-severe than in mild hydrocephalus (P < .01 and P= .02, respectively)." (PMID 28605426, 2017). "Consistent with the occurrence of hydrocephalus, there was increased expression of glial fibrillary acidic protein (GFAP)." (PMID 27336173, 2016). "Nevertheless, GFAP blood levels were elevated in only one of the five patients noted to have hydrocephalus." (PMID 26478912, 2015). "GFAP-Cre:VHLfl/fl mice exhibit severe locomotive defects, hydrocephalus, and increased lethality at 6 weeks that precludes their analysis in EAE." (PMID 26213713, 2015).
Hydrocephalus (continued). "In this study, the increased GFAP staining in the periventricular regions suggest that the periventricular white matter is an important site of brain injury in hydrocephalus, possibly from the stretch and compression which accompanies ventriculomegaly." (PMID 22938200, 2012). "Moreover, because the Ro1 receptor is a GPCR and is restricted to GFAP-positive cells, this model enables the investigation of specific signaling cascades that may cause hydrocephalus, which may lead to the development of novel drug-based therapeutics to treat this disorder." (PMID 22291910, 2012). "The present study has examined LRP-1, RAGE, Aβ, and GFAP in neonatal animals after intraventricular (obstructive) hydrocephalus was induced by kaolin injections into the cisterna magna at 1 day of age and ventriculomegaly had progressed until 21 days of age." (PMID 19470163, 2009). "Previous studies in a kaolin-induced kitten model of hydrocephalus demonstrated that shunting reduced the amount of GFAP present, but the results were quite variable, and GFAP levels began to rise over time." (PMID 17555588, 2007). "By utilizing a naturally occurring model of hydrocephalus, we have demonstrated that reactive astrocytosis, as discerned by Western blots of GFAP and GFAP-immunohistochemistry, increase in parallel with the onset and progression of hydrocephalus." (PMID 17555588, 2007). "The implantation of a shunt, either short or long term, was effective at reducing the increase in GFAP due to hydrocephalus, and led to a reduction in the overall presence of both astrocytes and microglia." (PMID 17555588, 2007). "The presence of GFAP+ astrocytes in our experimental CSF samples could, therefore, be a result of the brain’s response to hydrocephalus." (PMID 38291295, 2024). "Transgenic mice with TGF-β1 overexpression linked to the glial fibrillary acidic protein (GFAP) promoter in astrocytes develop hydrocephalus with no obstructions in the ventricular system." (PMID 26846184, 2016). "GFAP was reported in the CSF of elderly normal pressure hydrocephalus (NPH) patients compared with neurologically healthy age-matched controls suggesting a common pathophysiology involving astroglial damage in these types of hydrocephalus, but astroglial protection in FOH and LOH in the neonate." (PMID 24351234, 2013). "Additionally, by targeting the Ro1 receptor selectively to GFAP-positive cells (astrocytes and ependymal cells), we have developed a novel model of communicating hydrocephalus in which a single signaling system in a specific cell type leads to hydrocephalus." (PMID 22291910, 2012). "At this point, it remains unclear how the expression of the Ro1 receptor in GFAP-positive cells, namely astrocytes and ependymal cells, leads to hydrocephalus in the Ro1 model." (PMID 22291910, 2012). "Finally, Ecrg4 gene knockdown using RNA interference targeting Ecrg4a in zebrafish embryos led to a hydrocephalus-like phenotype and increased GFAP-positive cell proliferation." (PMID 21349154, 2011). "Our previous studies have shown that GFAP RNA levels increase with the progression of hydrocephalus in both a congenital model of rodent hydrocephalus (the H-Tx rat) and a kaolin model of induced hydrocephalus in kittens." (PMID 20507614, 2010). "While GFAP labeled astrocytes are commonly increased in hydrocephalus of all ages, probably in response to a wide variety of injury mechanisms, these astrocytes could also be related to Aβ clearance." (PMID 19470163, 2009). "Our previous studies have shown that the RNA level of Glial Fibrillary Acidic Protein (GFAP) specific for astrocytes, increases with the progression of hydrocephalus in both a congenital model of rodent hydrocephalus (H-Tx rat) and a kaolin model of induced hydrocephalus in kittens." (PMID 17555588, 2007).
Hydrocephalus (continued). "Conditions involving more obvious destruction of brain parenchyma, such as hydrocephalus or cavitating lesions, might also be expected to contribute to increased spillage of GFAP into the extracellular space, and subsequently into CSF and blood." (PMID 26478912, 2015). "An analysis of lateral ventricle size of P21 mice revealed expansion of ventricular width of 150% or more relative to wild type in 3/4 GFAP:Hi-Otx2 animals (data not shown), leading us to conclude that hydrocephalus is likely the cause of shortened lifespan in these mice." (PMID 22558385, 2012). "Remarkably, most GFAP-Cre; APCL/L mice experience early postnatal lethality due to congenital hydrocephalus." (PMID 38473403, 2024). "Using flow cytometry, we demonstrated that the GFAP-positive vesicles produced by glial cells colocalized mostly with AQP4 and that AQP4 levels were higher in samples from patients with obstructive hydrocephalus." (PMID 35346374, 2022). "Similar to our findings in hydrocephalus, there does seem to be more FDH in the AD brain tissue seen in the density of FDH+/GFAP+ astrocyte processes as well as a greater intensity of staining." (PMID 36614107, 2022). "This gain-of-function mouse model (GFAP.tTA/tetO.IKK2-CA, abbreviated IKK2-CA from hereon) is characterized by a robust neuroinflammatory phenotype with lethal hydrocephalus formation in early postnatal development." (PMID 28193238, 2017). "It is likely that cells of type B, which have been shown to express GFAP without vimentin expression and type A neuroprogenitor cells, can also be affected after the induction of hydrocephalus because their proliferation was found to decrease." (PMID 35193620, 2022). "Indeed, it has been found that glial fibrillary acidic protein (GFAP) RNA levels, characteristic of astrocytes, rise along with the evolution of hydrocephalus." (PMID 34440681, 2021). "Blood and cerebrospinal fluid (CSF) of children with TBM and hydrocephalus taken on admission and over 3 weeks were analyzed for the neuromarkers S100B, neuron-specific enolase (NSE), and glial fibrillary acidic protein (GFAP), in addition to multiple inflammatory markers." (PMID 28605426, 2017). "At P0, when no hydrocephalus was present, GFAP expression was prominent in the ependyma of the lateral ventricles and in the subependymal zone of Mpdz−/− mice." (PMID 28500065, 2017). "Unlike the control SVZ, mice with hydrocephalus show that more GFAP+ SVZ astrocyte is detected in the parenchyma or in the extra-SVZ." (PMID 27243144, 2016). "Ependymal damage is well documented in hydrocephalus as is astrogliosis so it is perhaps not surprising to find GFAP in CSF as a consequence of specific insults." (PMID 24351234, 2013). "GFAP was significantly raised only in CSF from post-haemorrhagic hydrocephalus while MBP was significantly raised in post-haemorrhagic and in spina bifida with hydrocephalus infants." (PMID 24351234, 2013). "The finding that GFAP is not present in CSF from FOH and LOH must therefore indicate protection of these cells from damage in these forms of hydrocephalus." (PMID 24351234, 2013).
myelitis (37 papers, 2011 to 2025). An inflammatory process affecting the spinal cord. "In another retrospective study of 16 patients with GFAP-IgG-associated myelitis, the median CSF protein concentration was 729 mg/L and approximately 2,344 mg/L." (PMID 38020648, 2023). "In our study, GFAP-IgG-associated myelitis was prevalent in adults, consistent with the results of previous studies." (PMID 38020648, 2023). "Among the 14 patients with GFAP-IgG-associated myelitis, the condition was more common in males (71.4%), with a median age of onset of 36.5 years, and more common in adults than in children (35.7%)." (PMID 38020648, 2023). "Cerebellar meningeal enhancement appeared to occur more frequently in patients with GFAP-IgG-associated myelitis." (PMID 38020648, 2023). "Among the 14 patients with GFAP-IgG-associated myelitis who were included, nine, two, and three were positive for GFAP-IgG in CSF, CSF and serum, and serum, respectively." (PMID 38020648, 2023). "One study reported that the spinal cord central canal, punctate, or leptomeningeal enhancement is reportedly typical of GFAP-IgG-associated myelitis." (PMID 38020648, 2023). "In cranial MRI, patchy gadolinium enhancement was less common in patients with GFAP-IgG-associated myelitis than in those with MOG-IgG-associated myelitis, with a significant difference (p < 0.05)." (PMID 38020648, 2023). "In our study, 12 (85.7%) and 9 (64.3%) patients with GFAP-IgG-associated myelitis had elevated CSF leukocytes and CSF proteins, respectively, and all 13 patients in a previous study had increased CSF leukocytes." (PMID 38020648, 2023). "Among the 14 patients with GFAP-IgG-associated myelitis, 11 (78.6%) had intracranial lesions, which mainly manifested as high signals on T2 weighted image/fluid-attenuated inversion recovery (T2WI/FLAIR) sequences (Figures 3A1,A2)." (PMID 38020648, 2023). "Glial fibrillary acidic protein-immunoglobulin G (GFAP-IgG)-associated myelitis and myelin oligodendrocyte glycoprotein-IgG (MOG-IgG)-associated myelitis have rarely been compared." (PMID 38020648, 2023). "These include spinal cord sarcoidosis, paraneoplastic myelopathies, myelitis associated with glial fibrillary acidic protein (GFAP)-IgG, and myelitis associated to systemic immune-mediated disorders (e.g., Behcet, systemic lupus erythematosus)." (PMID 36419536, 2022). "Nevertheless, in the recent publication of 13 patients with LETM associated to GFAP-antibodies, all have extra-spinal symptoms simultaneously or preceding myelitis onset, on the contrary to our patients." (PMID 32326965, 2020). "Therefore, compared to MOG-IgG-associated myelitis, GFAP-IgG-associated myelitis appears to have a later age of onset, is relatively rare in patients with optic neuritis, and is relatively common in those with impaired consciousness." (PMID 38020648, 2023). "In our study, LETM was common in patients with GFAP-IgG-associated myelitis." (PMID 38020648, 2023). "The median age of onset of GFAP-IgG-associated myelitis was later than that of the MOG-IgG group." (PMID 38020648, 2023). "Among the 14 patients with GFAP-IgG-associated myelitis, 2 (14.3%) had isolated myelitis in adults." (PMID 38020648, 2023). "Our CSF protein was approximately 1837 mg/L, including three cases >1 g/L; therefore, we hypothesize that protein elevation is more pronounced in the CSF of patients with GFAP-IgG-associated myelitis." (PMID 38020648, 2023). "Patients with prodromal symptoms in GFAP-IgG-associated myelitis are relatively common (42.9% in our study), viral infections are common, and some studies have shown that autoimmune GFAP-A may be associated with herpes simplex virus infection." (PMID 38020648, 2023). "Therefore, we hypothesized that GFAP-IgG-associated myelitis is more likely to be associated with elevated CSF protein levels and is more significantly increased than MOG-IgG-associated myelitis, which may indicate a severe inflammatory response in the CNS." (PMID 38020648, 2023).